SLC3A2 (solute carrier family 3 member 2)
Diseases named in the same sentence as SLC3A2 in open-access papers (continued):
Sharing a sentence is not in itself a finding about the gene and the disease.
tumor (continued). "Next, we employed a modified chick embryo chorioallantoic membrane (CAM) assay to assess the role of SLC3A2 in tumor growth and metastasis in vivo." (PMID 29179459, 2017). "Overexpression of SLC3A2 in NCI-N87 cells resulted in a significantly increase in tumor weight compared to control cells." (PMID 29179459, 2017). "SLC3A2 establishes tumor cell: SLC3A2-overexpressing NIH-3T3 fibroblasts develop malignant tumors in athymic mice." (PMID 27626312, 2016). "To further confirm this association, we interrogated the TCGA database for SLC3A2 and DDIT3 levels in Fascin high and low tumor samples." (PMID 27819326, 2016). "Overexpression of CD98hc (SLC3A2) occurs in a variety of cancers and is suspected to contribute to tumor growth." (PMID 24359579, 2013). "Transcripts for SLC3A2 are shifted to a higher molecular weight, indicating the inclusion of various combinations of exons 2, 3 and 4 in tumor samples that are much less prevalent in normal tissue." (PMID 17192196, 2006). "In addition, tumor volume was significantly decreased in the HnRNPU-knockdown group, and this effect was reversed by SLC3A2 and SLC7A11 overexpression." (PMID 41310105, 2025). "We also found that c‐Myc overexpression elevated SLC1A5/SLC3A2/SLC7A5 expression in RTN4IP1‐deficient cells, and promoted cell proliferation as well as tumor growth upon RTN4IP1 knockdown, demonstrating the essential role of SLC1A5/SLC3A2/SLC7A5 in RTN4IP1‐mediated cell proliferation." (PMID 39757767, 2025). "Our findings revealed that SLC3A2 is expressed in both malignant tumor cells and immune cells." (PMID 39926285, 2025). "Moreover, SLC3A2 expression increased during progression, as Tfh tumor cells in the relapsed/refractory (RR) group expressed higher levels of SLC3A2 than those in the newly diagnosed (ND) group." (PMID 40344476, 2025). "Finally, our study confirmed the oncogenic role of SLC3A2 in the proliferation and migration of tumor cells in vitro." (PMID 39926285, 2025). "SLC3A2 transcripts were highly and preferentially expressed in Tfh tumor cells." (PMID 40344476, 2025). "Subsequently, we investigated whether the tumor‐promoting effects of SLC3A2 were mediated by arginine uptake." (PMID 40344476, 2025). "Furthermore, it has been confirmed that efficient uptake of glutamine and leucine through SLC1A5, SLC7A5, and SLC3A2 can enhance metabolic capacity and effector functions of NK and T cells targeting tumors for improved tumor recognition and infiltration." (PMID 39951434, 2025). "The results showed that SLC1A5/SLC3A2/SLC7A5 knockdown diminished tumor growth in vivo." (PMID 39757767, 2025). "In summary, we discovered that the disulfidptosis-related gene SLC3A2 exhibits high expression levels in NPC and HNSC tissues, and its presence is closely linked to tumor stage, which could predict poor prognosis in these patients." (PMID 39926285, 2025). "Finally, in vitro experiments demonstrated that SLC3A2 stimulates tumor cell proliferation and migration." (PMID 39926285, 2025). "Furthermore, the SLC3A2 up-regulation in cancer cells has suppressed cystine uptake, leading to an increase in tumor lipid peroxidation, tumor ferroptosis, and tumor regression." (PMID 39286654, 2024). "Moreover, Ki67 staining showed that the proliferation ability of tumor cells in vivo was also significantly inhibited after knockout of SLC3A2 and SLC7A5." (PMID 38267663, 2024). "Thus, YTHDC2 indirectly inhibits SLC3A2 to induce ferroptosis in cancer cells, resulting in impairing tumor growth and inducing lipid peroxidation." (PMID 38705513, 2024). "SLC3A2 promotes both intra- and extra-cellular processes to enhance tumor progression." (PMID 38705513, 2024). "Moreover, using the TIMER database, we found that the expression of NUBPL and ACTB was closely related to tumor purity, while the correlation of SLC3A2 and DSTN with tumor purity was less pronounced." (PMID 39896807, 2024).
tumor (continued). "Therefore, our study provides a ground‐breaking exploration into the molecular mechanism by which downregulation of SLC3A2 expression mediates immune escape and accelerates disulphide death in tumour cells, further advancing the progression of TSCC." (PMID 37927242, 2023). "Our results further indicated that SLC3A2 was associated with tumor infiltration of cytotoxic T cell but not other immune cells among BC TME." (PMID 37484811, 2023). "Therefore, subsequent studies on FKBP1A/SLC3A2 axis need to focus on the exosomal communication between tumor cells and Th9 cells in BC TME." (PMID 37484811, 2023). "These research findings suggest that SLC3A2 may serve as a potential therapeutic target for tumours." (PMID 37927242, 2023). "miR-142-3p has been found to highly express in the M1 macrophages of hepatocarcinoma tissue, which could affect the production of GSH, Fe2+, and MDA, promoting ferroptosis of the M1 macrophages by targeting SLC3A2, thus facilitating tumor metastasis." (PMID 37369681, 2023). "Additionally, targeted inhibition of SLC3A2 expression or function has been found to suppress the proliferation and invasive abilities of tumour cells and increase sensitivity to chemotherapy drugs." (PMID 37927242, 2023). "We next addressed whether expression of p-GCN2- or GCN2-dependent mRNA transcripts correlated with expression of 4F2 (SLC3A2) in human tumor samples." (PMID 36107759, 2022). "Given both malignant phenotype of cancer cell and tumor microenvironment could affect the clinical outcomes, we further investigated the potential role of SLC3A2 in these aspects." (PMID 35992269, 2022). "Recent studies have found that SLC3A2 is up‐regulated in a variety of tumour tissues." (PMID 35567291, 2022). "Overall, these in vitro studies preliminarily suggest that SLC3A2 may be significant in tumor initiation and progression." (PMID 35992269, 2022). "Importantly, IGN523, a humanized anti-CD98 (anti-SLC3A2) monoclonal antibody has been tested for relapsed or refractory acute myeloid leukemia, and preclinical data showed effective anti-tumor activity in xenograft models." (PMID 35812393, 2022). "Few studies have researched the role of SLC3A2 in anti-tumor immunity." (PMID 35992269, 2022). "SLC3A2 was overexpressed in tumor tissues compared with normal tissues." (PMID 35057861, 2022). "Similarly, CCL26 also showed a moderate correlation with higher SLC3A2 expression across cancer types, which has been reported to be a key element in tumor invasion and chemoresistance." (PMID 35992269, 2022). "Additionally, SLC3A2 deficiency suppressed tumor growth in nude mice, and the expression of GPX4 was upregulated in sh-SLC3A2 tumor tissues compared to sh-NC tumor tissues by IHC staining." (PMID 35057861, 2022). "Moreover, SLC7A5 and SLC3A2 enhance the metabolic capacity and effector function of tumor-directed CAR-NK and T cells." (PMID 36090994, 2022). "In addition, we analyzed the protein level of SLC3A2 in tumor slices using immunohistochemical staining." (PMID 35992269, 2022). "Addition of essential amino acids or expression of 4F2 (SLC3A2) partially restored growth following loss of GCN2, suggesting that GCN2 targeting of SLC transporters is required for amino acid homeostasis needed to sustain tumor growth." (PMID 36107759, 2022). "Upregulation of Slc3a2 enhances the tumor specificity of NK cells." (PMID 35923893, 2022). "Xenograft tumor model was used to determine the role of SLC3A2 in tumor growth." (PMID 35057861, 2022). "It is necessary to explore the function of SLC3A2 in patients’ tumor samples." (PMID 35992269, 2022). "We analyzed the CRISPR-based experimental data using DepMap and found that SLC3A2 could affect cell proliferation in the majority of tumor cell-lines." (PMID 35992269, 2022). "On the other hand, whether SLC3A2 expressed in tumors affects the tumor microenvironment was clarified in the present study." (PMID 35992269, 2022).
tumor (continued). "Moreover, tumours with high SLC38A2 expression were also commonly represented in the poor prognostic high SLC cluster (SLC1A5+/SLC7A5+/SLC3A2+)." (PMID 33028955, 2021). "Additionally, interferon-γ from CD8+ T cells can promote tumor cell ferroptosis by downregulating SLC3A2 and SLC7A11, impairing tumor cystine uptake and disrupting tumor cell redox homeostasis." (PMID 34830482, 2021). "Interestingly, SLC3A2 deletion in the same cell types showed intact mTORC1 activity and tumor growth rate, but the cells were sensitive to SLC7A5 inhibition via treatment with JPH203." (PMID 33953707, 2021). "In addition, after knockdown of BRD4 or under (+)-JQ1 (an inhibitor of the tumor-driver bromodomain protein BRD4), the expressions of ferroptosis-associated genes GPX4, SLC7A11, and SLC3A2 are downregulated." (PMID 34222241, 2021). "High expression of either SLC7A11 and SLC3A2 has been previously reported in several tumor types." (PMID 33672555, 2021). "It is reported that inhibition of SLC3A2 promotes ferroptosis in both tumor cells and normal cells." (PMID 34434214, 2021). "First, we used the METABRIC cohort to investigate the possible correlation between mRNA and clinical outcome; this analysis revealed that patients with SLC7A5+SLC3A2+ tumours had a significantly worse recurrence, distant metastasis and shorter survival (p = 0.01) compared to other subgroups." (PMID 32093034, 2020). "Gene SLC3A2 and APC, which were associated with metastasis and neoplasia, were included." (PMID 33425983, 2020). "Intriguingly, IFNγ released from CD8+ T cells downregulates the expression of SLC7A11 and of SLC3A2, another subunit of the glutamate-cystine antiporter system (xCT), henceforth, limiting the uptake of cystine by tumor cells, promoting tumor cell lipid peroxidation and ferroptosis." (PMID 32516941, 2020). "Therefore, it is particularly interesting to observe the correlation with SLC3A2 another stem cell related marker in our samples which confirms its link to tumor stem cell abundance." (PMID 31998639, 2019). "High expression of SLC3A2 mRNA was significantly associated with hormone receptor-negative (ER− and PR−) tumours (p ≤ 0.001) but not with HER2+ BC." (PMID 29545595, 2018). "Earlier report examining the expression levels of membrane proteins showed SLC3A2 was markedly up-regulated in GC cells and GC tumor tissues and may serve as a potential biomarker for molecular imaging-based detection of GC." (PMID 29179459, 2017). "SLC3A2 exerted promotion effects on GC tumor growth and metastasis." (PMID 29179459, 2017). "Besides, HNSC patients with tumor progression showed higher SLC3A2 expression." (PMID 39926285, 2025). "In addition, we confirmed that SLC3A2 levels increased with tumor progression in Group2." (PMID 40344476, 2025). "SLC3A2 loss impaired tumor growth without affecting body weight." (PMID 40344476, 2025). "Upregulating expression of SLC3A2 in immune cells may augment the efficacy of tumor immunotherapy." (PMID 38223725, 2024). "Thus, SLC3A2 holds the potential to influence tumor cell proliferation, migration, and metabolism." (PMID 38977800, 2024). "Similarly, SLC3A2 promotes tumor growth in osteosarcoma through the PI3K/AKT signaling pathway." (PMID 38705513, 2024). "In addition, SLC3A2 was highly expressed in tumor compared with matched normal tissues by IHC." (PMID 35057861, 2022). "However, many studies have shown that SLC3A2 is highly expressed in most tumor types." (PMID 36233241, 2022). "It has been reported that SLC3A2 deletion results in a downregulation of SLC7A11 levels, indicating that SLC3A2 is required to maintain SLC7A11 stability and its deficiency will impair the integrity of the system Xc−, thus sensitizing tumor cells to ferroptosis." (PMID 33425217, 2020).
tumor (continued). "A study found that immune checkpoint inhibitors activate and induce CD8+ T cells to secrete interferon‐gamma (IFN‐γ), which negatively regulates the expression of the Xc system components SLC3A2 and SLC7A11 on the surface of tumor cells." (PMID 41560416, 2026). "The cell adhesion molecule binding cluster in TuNEPs contained tumorigenic proteins such as ITGA2, CD151, CD9, SLC3A2, and BSG, all known to have an impact on the tumor microenvironment." (PMID 40751052, 2025). "Immunofluorescence-stained tumor sections confirmed the suppression of SLC7A11 and SLC3A2 expression in all medication groups." (PMID 40367177, 2025). "Specifically, an elevation in the expression levels of PRN1, OXSM, SLC3A2, and CD2AP were observed in tumor tissues, while the expression levels of DSTN, FLNA, TLN1, IQGAP1, MYL6, NCKAP1, and NDUFS1 declined in tumor tissues." (PMID 39995998, 2025). "The MIF/SLC3A2 axis activated the AKT/GSK-3β signaling pathway, leading to increased tumour cell proliferation and metastasis." (PMID 41154605, 2025). "IFN-γ released from CD8+ T cells downregulates the expression of SLC7A11/SLC3A2 by activating the JAK/STAT pathway, which promotes tumor ferroptosis, contributing to the antitumor efficacy of immunotherapy." (PMID 41373022, 2025). "Specifically, IFN–γ released from ICI–activated CD8+ T cells downregulates system xc– components (SLC3A2 and SLC7A11) in tumor cells, thereby promoting lipid peroxidation and ferroptosis." (PMID 40895556, 2025). "SLC3A2 acts as a chaperone for LAT1 and xCT, enhancing amino acid transport while supporting integrin-mediated tumour invasion." (PMID 41154605, 2025). "Interferon-gamma (IFN-γ) regulates the expression of SLC3A2, SLC7A11, and ACSL4, subsequently inducing immunogenic ferroptosis in tumor cells." (PMID 40260246, 2025). "This led to the release of IFN-γ, which effectively inhibited the expression of SLC3A2 and SLC7A11 in tumor cells." (PMID 38853203, 2024). "This inference is bolstered by a robust Spearman correlation underscoring the parallelism between increasing SLC3A2 expression and TIDE scores, implying enhanced tumor escape mechanisms and deteriorating prognoses (R = 0.453, P < 0.001)." (PMID 38977800, 2024). "Inhibiting SLC3A2 and SLC7A11 can decrease intracellular cystine levels in tumor cells, increasing their sensitivity to ferroptosis induction." (PMID 39273090, 2024). "As core effector cells in antitumor immunity, CD8+ T cells enhance tumor cell lysis by secreting interferon-γ (IFN-γ), which inhibits the expression of SLC7A11 and SLC3A2—subunits of the system Xc– in tumor cells." (PMID 39850905, 2024). "In 50 paired tumors and adjacent non-tumor tissues from TCGA COREAD database, 27 of 50 (54 %) CRC samples showed upregulation of SLC1A4, SLC1A5, SLC7A11 and SLC3A2 simultaneously, and 17 of 50 (34 %) CRC samples showed upregulation of three transporter genes." (PMID 39079386, 2024). "The expression of SLC7A11, SLC3A2, RPN1 and NCKAP1 were found to be upregulated in the tumor tissues compared with that in the corresponding normal tissues from the TCGA data." (PMID 38528532, 2024). "Immunotherapy-activated CD8+ T cells can release IFN-γ to downregulate the system Xc− functional subunits SLC3A2 and SLC7A11, impeding tumor cells from acquiring cystine and thus leading to lipid peroxidation and ferroptosis in cancer cells." (PMID 39614322, 2024). "Reduced SLC3A2 expression in OSCC promotes immune evasion and tumour progression by impairing T lymphocyte function." (PMID 37927242, 2023). "It has been confirmed that the regulation of the glutamate/cysteine reverse transport system key proteins can affect ferroptosis in tumor cells, such as SLC38A1, SLC1A5, SLC3A2, and SLC7A11." (PMID 37369681, 2023). "CD8+ T cells promote ferroptosis in tumor cells by releasing interferon-gamma (IFN-γ) and suppressing the expression of SLC3A2 and SLC7A11 in tumor cells." (PMID 37238692, 2023).
tumor (continued). "In this process, interferon-γ (IFNγ) derived from activated CD8+ T cells has been shown to defer the expression of SLC3A2 and SLC7A11, inhibiting tumor cell cystine import and sensitizing tumor cells to ferroptosis." (PMID 37840106, 2023). "These molecules inhibit the expression of Solute Carrier Family 7 Member 11 (SLC7A11) and Solute Carrier Family 3 Member 2 (SLC3A2), two subunits of the xc system, and further direct the target (tumor) cell toward ferroptosis." (PMID 38139106, 2023). "Before and after the treatment of QLD, we measured several ferroptosis-related biomarkers (SLC7A11, SLC3A2, GPX4, and FSP1) in tumor tissues from the patients with CRPC." (PMID 37576395, 2023). "Recently, ACT of T-cells targeting mutant proteins (SLC3A2, KIAA0368, CADPS2 and CTSB) detected in a patient tumor in combination with interleukin two have been demonstrated to induce tumor regression." (PMID 36910138, 2023). "Existing SLC transporter inhibitors mostly focused on tumor cells, and targeting SLC1A5, SLC3A2, or SLC7A5 has shown anti-tumor efficacy." (PMID 37277776, 2023). "SLC3A2 has been identified as a promising biomarker for HNSCC radioresistance and a target for tumor radiosensitization." (PMID 35406454, 2022). "Again, using a tumor tissue array containing patient samples, we stained for p-GCN2-T899 and 4F2 (SLC3A2)." (PMID 36107759, 2022). "Specifically, interferon gamma released from CD8+ T cells restrain the synthesis of GSH through downregulating SLC3A2 and SLC7A11, therefore leading to the accumulation of peroxidated phospholipid and ferroptosis in tumor cells." (PMID 35874826, 2022). "SLC3A2-targeted CAR-T cell is a novel, efficacious, and potentially safe approach for tumor cell therapies." (PMID 35935930, 2022). "By contrast, in the merged pan-cancer cohort, SLC3A2 expression was significantly correlated with lower levels of GZMA and INFG, which were cytotoxic molecules that matter in anti-tumor responses." (PMID 35992269, 2022). "CD8+T cells activated by anti-PD-L1 immunotherapy secrete IFN-γ, which significantly down-regulates the expression of SLC3A2 and SLC7A11 in tumor cells, resulting in the decrease of cystine uptake, thus promoting the occurrence of ferroptosis." (PMID 36387286, 2022). "Studies have shown that the expression of TYRO3 is increased in immunotherapy-resistant tumor cells, and TYRO3 signaling pathway inhibits the ferroptosis of tumor cells by up-regulating the expression of SLC3A2 and other genes." (PMID 36387286, 2022). "By regulating amino acid transport, SLC3A2 and SLC7A5 play an important role in tumor growth and oxidative stress control." (PMID 35057861, 2022). "Similar to supplementation with EAA, overexpression of 4F2 (SLC3A2) in GCN2 KO tumors partially rescued growth and restored tumor amino acid levels." (PMID 36107759, 2022). "Through the HPA database, we found that three genes (ABCC9, AHNAK, and DIP2C) had low expression in patients with tumours, whereas eight genes (PLOD1, SLC3A2, RUNX2, RAD9A, CHMP4C, DARS2, CLIC3, and POU5F1) were highly expressed." (PMID 36685927, 2022). "IFN-γ released by CD8+ T cells downregulates the expression of two subunits of the glutamate-cysteine anti-transport system, SLC3A2, and SLC7A11, inhibits the uptake of cystine by tumor cells and promotes tumor cells lipid peroxidation and ferroptosis." (PMID 36060256, 2022). "Interferon gamma (IFN-γ) secreted by CD8+ T cells downregulates the expression of SLC3A2 and SLC7A11 in tumour cells, impairs the uptake of cystine and, as a consequence, promotes lipid peroxidation and ferroptosis in tumour cells." (PMID 35804831, 2022).